QSOX1 (quiescin sulfhydryl oxidase 1)
Description:
Catalyzes the oxidation of sulfhydryl groups in peptide and protein thiols to disulfides with the reduction of oxygen to hydrogen peroxide. Plays a role in disulfide bond formation in a variety of extracellular proteins. In fibroblasts, required for normal incorporation of laminin into the extracellular matrix, and thereby for normal cell-cell adhesion and cell migration.
Synonyms: QSCN6; Q6
Tractability: Small molecule: a structure with a bound ligand is known; it has a binding pocket of medium quality. Antibody: UniProt places it where antibodies can reach, with high confidence; its Gene Ontology location is reachable by antibodies, with high confidence; UniProt predicts a signal peptide or a membrane-spanning region. PROTAC: ubiquitination databases record sites on it; its protein half-life has been measured; a small molecule that binds it is known.
Target class: Enzyme; Oxidoreductase
Gene: Protein-coding gene on chromosome 1 (180,154,869 to 180,204,030, forward strand). Ensembl gene ENSG00000116260.
Subcellular location: Golgi apparatus membrane (Isoform 1); Secreted; Secreted (Isoform 2)
Subcellular location (Human Protein Atlas): Golgi apparatus; Vesicles; Predicted to be secreted
Pathways (Reactome):
Metabolism of proteins: Post-translational protein phosphorylation; Regulation of Insulin-like Growth Factor (IGF) transport and uptake by Insulin-like Growth Factor Binding Proteins (IGFBPs)
Hemostasis: Platelet degranulation
Immune System: Neutrophil degranulation
Gene Ontology:
Molecular function: FAD binding; flavin-dependent sulfhydryl oxidase activity; protein disulfide isomerase activity; thiol oxidase activity
Biological process: extracellular matrix assembly; negative regulation of macroautophagy; protein folding
Cellular component: extracellular exosome; extracellular region; Golgi apparatus; Golgi membrane; endoplasmic reticulum lumen; platelet alpha granule lumen; specific granule lumen; tertiary granule lumen
Genetic constraint (gnomAD): Loss-of-function variants: 38 observed, 71.69 expected, observed/expected ratio (o/e) 0.53, 90% interval 0.41 to 0.69. The upper end of that interval is the gene's LOEUF score, 0.69, which puts it in group 2 of 6, group 1 being the genes least tolerant of losing a copy. Missense variants: 920 observed, 949.6 expected, observed/expected ratio (o/e) 0.97, 90% interval 0.92 to 1.02. Synonymous variants: 390 observed, 396.74 expected, observed/expected ratio (o/e) 0.98, 90% interval 0.9 to 1.07.
Homologues: Orthologues: chimpanzee QSOX1 (99% identical), macaque QSOX1 (96% identical), pig QSOX1 (76% identical), rabbit QSOX1 (76% identical), dog QSOX1 (74% identical), rat Qsox1 (73% identical), mouse Qsox1 (73% identical), guinea pig QSOX1 (60% identical), zebrafish qsox1 (40% identical), tropical clawed frog qsox1 (38% identical), Drosophila melanogaster Qsox1 (23% identical), Drosophila melanogaster Qsox2 (22% identical), and 3 more. Paralogues in human: QSOX2 (35% identical).
Diseases named in the same sentence as QSOX1 in open-access papers:
QSOX1 is named in the same sentence as 39 diseases in open-access papers, as found by Europe PMC text mining. Sharing a sentence is not in itself a finding about the gene and the disease. The quoted sentences say what the papers report.
breast carcinoma (15 papers, 2012 to 2023). "QSOX1 is expressed at high levels in a variety of human adenocarcinomas and is also over-produced by stromal fibroblasts associated with aggressive breast carcinomas." (PMID 32064042, 2020). "It has been shown that downregulation of QSOX1 reduces cell-cell adhesion, and thus increases tumour migration and metastasis in breast cancer cell lines." (PMID 34090364, 2021). "QSOX1 contributes to metastasis-related ECM rearrangement in breast cancer, and anti-QSOX1 antibodies and LMW inhibitors suppressed the growth of cancer cells in mouse models." (PMID 34770976, 2021). "QSOX1 transcripts were found at higher levels in the stroma of aggressive breast carcinomas, and QSOX1 expression is up-regulated in a variety of adenocarcinomas including breast, lung, pancreas, and prostate." (PMID 32064042, 2020). "To analyze QSOX1 expression in tumor stroma in situ, we performed immunohistochemical (IHC) staining on paraffin sections of biopsies from breast cancer patients." (PMID 32064042, 2020). "Based on this finding and the increased QSOX1 expression in the stroma of aggressive breast carcinomas, we developed monoclonal antibody inhibitors with the aim of preventing QSOX1 from participating in pro-metastatic ECM remodeling." (PMID 32064042, 2020). "In breast cancer, it is reported that high expression of QSOX1 leads to the reduction of tumorigenesis and correlates to the prognosis of the patients." (PMID 30336636, 2018). "TFDP1 is involved in the cell cycle and contributes to hepatocellular carcinomas, SMAD1 is involved in multiple pathways, and QSOX1 plays roles in some cancers such as breast cancer and neuroblastoma." (PMID 29686831, 2018). "Altogether, our results demonstrate for the first time a role of QSOX1 in autophagy in breast cancer cells and tumors." (PMID 24475161, 2014). "We identified a novel extended 3′UTR form of the QSOX1 transcript and showed that the gene is indeed overexpressed in breast cancers of poor prognosis." (PMID 23460839, 2013). "We demonstrate here that the transcript for QSOX1 is highly overexpressed in some breast cancers, with a strong correlation between expression level and prognostic index." (PMID 23460839, 2013). "We further sought to confirm experimentally both the existence of this new 3′ QSOX1 mRNA extension and the upregulation of QSOX1 mRNA levels in breast cancer tissue." (PMID 23460839, 2013). "We investigated QSOX1 cDNA derived from T47D breast carcinoma cells by RT-PCR and 3′-RACE PCR and identified a novel extended form of QSOX1 transcript, containing a long 3′UTR, nearly double the size of the previously reported QSOX1 cDNA, and confirmed its 3′ end nucleotide sequence using RACE-PCR." (PMID 23460839, 2013). "Transcription of QSOX1 in oestrogen receptor-expressing breast cancer cell lines has also been documented in two further studies, although in one of these expression was found to be repressed by 17β-oestradiol whereas in the other such treatment resulted in a modest induction." (PMID 23460839, 2013). "Of particular interest was the identification among the found genes, of QSOX1, which encodes quiescin Q6 sulfhydryl oxidase 1, because no information existed at the time of its association with breast cancer." (PMID 23460839, 2013). "The discrepancies between our results on breast cancer cells and Katchman's results on pancreatic cells could be explained by differential expression of QSOX1 isoforms and its substrates availability." (PMID 23098186, 2012). "Of the four highest ranked genes, which had no detectable expression in normal breast tissue in the SAGE database (with P<0.01), we chose to focus on QSOX1 which encodes quiescin Q6 sulfhydryl oxidase 1, which has not been previously associated with breast cancer." (PMID 23460839, 2013). "Our results showed that QSOX1 overexpression leads to an increase in p62 and LC3-II levels and an increase in the number of GFP-LC3 puncta in breast cancer cells." (PMID 24475161, 2014).
breast carcinoma (continued). "Expression of QSOX1 protein in breast tumors tissue microarray (TMA) and in a panel of breast cancer cell lines was used to confirm our informatics analysis." (PMID 23536962, 2013). "Finally, analysis of TCGA database revealed that the combined high expression of NSUN2, YBX1 and QSOX1 predicted the poorest overall survival in lung adenocarcinoma (LUAD), breast cancer (BRCA) and hepatocellular carcinoma (HCC)." (PMID 37161388, 2023). "Previous studies have shown that QSOX1 is overexpressed in tumor tissues and promotes the invasion and metastasis of HCC, lung cancer, prostate cancer, and breast cancer cells." (PMID 34350181, 2021). "To investigate malignant cell mechanisms for which QSOX1 might play a key role, we suppressed QSOX1 protein expression using short hairpin (sh) RNA in ER+ Luminal A-like MCF7, ER+ Luminal B-like BT474 and ER- Basal-like BT549 breast cancer cell lines." (PMID 23536962, 2013). "QSOX1 was found to be overexpressed in breast cancer on mRNA level in SAGE expression library, but expressed below the detection level in the matched normal SAGE library (P = 0.01) and was also detected in breast cancer tissue but not normal breast in the EST database." (PMID 23460839, 2013).
prostate carcinoma (8 papers, 2012 to 2025). A carcinoma that arises from epithelial cells of the prostate gland. "High expression of QSOX1 has been linked to vascular invasion, neural invasion, prostate extension, increased pT stage, and higher pathological tumor stage in prostate cancer." (PMID 38817605, 2024). "QSOX1 has been reported to be overexpressed in diverse tumor types such as pancreatic, breast, and prostate cancers, and is associated with a proliferative and invasive phenotype." (PMID 26158899, 2015). "High amounts of QSOX1 were reported in breast, pancreas and prostate cancers therefore we can consider TCs as important players in the maintenance of oxidative microenvironment preventing tumourigenesis." (PMID 24826900, 2014). "It turns out that QSOX1 is overexpressed during the early stages of prostate cancer, and in pancreatic tumor cells." (PMID 23098186, 2012). "QSOX1 (quiescin sulfhydryl oxidase 1) has an emerging role in cancer and was shown to be overexpressed in several malignancies including breast, pancreas, and prostate cancer." (PMID 32536039, 2020). "QSOX1 RNA is elevated when expression of the transcriptional regulator NKX3.1 is reduced in prostatic intraepithelial neoplasia, suggesting that QSOX1 expression may contribute to prostate cancer progression." (PMID 26158899, 2015). "Moreover in a rodent model of prostate cancer, QSOX1 is highly overexpressed in prostatic hyperplasia and intraepithelial neoplasia (PIN) lesions of mice lacking the transcriptional regulator and tumour suppressor gene Nkx3.1." (PMID 23460839, 2013). "QSOX1 is overexpressed in prostate cancers and in pancreatic adenocarcinoma." (PMID 23098186, 2012).
lung carcinoma (7 papers, 2018 to 2025). "In this study, we identified lung cancer-secreted protein QSOX1 as a lung cancer-selective biomarker candidate with a proteomics approach and validated its increase in tissues and serum of lung cancer patients." (PMID 30336636, 2018). "Higher levels of QSOX1 were also uniquely detected in lung cancer tissues, among several other solid cancers, by immunohistochemistry." (PMID 30336636, 2018). "So far, we have shown that lung cancer tissues had higher levels of QSOX1 proteins, of which levels were somewhat lung cancer-unique compared to other cancers tested." (PMID 30336636, 2018). "The Western blot data were quantified by densitometric analysis and the graph shows that 48 patients out of 56 (82.2%) showed an increase of QSOX1 protein levels in the lung cancer tissues, in comparison to adjacent normal tissues." (PMID 30336636, 2018). "Quiescin sulfhydryl oxidase (QSOX1) was selected as a biomarker candidate from the enriched proteins in the secretion of lung cancer cells." (PMID 30336636, 2018). "From the results of the immunohistochemical analysis, high levels of QSOX1 protein were detected in lung cancer cells." (PMID 30336636, 2018). "From the results of the Western blot verification in lung cancer tissues, it can be confirmed that QSOX1 is up-regulated in lung cancer tissues." (PMID 30336636, 2018). "In conclusion, QSOX1 might be a lung cancer tissue-derived biomarker and be involved in the promotion of lung cancers, and thus can be a therapeutic target for lung cancers." (PMID 30336636, 2018). "Mechanistic studies show that NSUN2 regulates the m5C modification of QSOX1, and YBX1 enhances QSOX1 translation in an m5C-dependent manner, thereby promoting resistance to EGFR-mutant lung cancer." (PMID 40370440, 2025). "The other upregulated genes ELFN2, QSOX1, and MUC1 have been shown to directly promote metastasis in various cancers, including lung cancer." (PMID 34172784, 2021). "However, supplementing primary NF cultures with conditioned medium from H460 human lung cancer cells, which do not secrete detectable levels of QSOX1, increased QSOX1 expression to a comparable level as seen in CAFs." (PMID 32064042, 2020).
hepatocellular carcinoma (6 papers, 2018 to 2025). A malignant tumor that arises from hepatocytes. "It has been revealed that hepatocellular carcinoma (HCC) cells with heightened intracellular quiescin sulfhydryl oxidase 1 (QSOX1) exhibit increased sensitivity to sorafenib." (PMID 39857439, 2025). "QSOX1 may impair Nrf2 activation in hepatocellular carcinoma cells, suggesting that the over-expression of hepatic QSOX1 may promote oxidative stress." (PMID 38956533, 2024). "For its endosomal signaling, quiescin sulfhydryl oxidase 1 (QSOX1) has been identified as a cellular pro-oxidant, which accelerates ubiquitination-mediated degradation of EGFR and its intracellular endosomal trafficking in hepatocellular carcinoma (HCC) cells." (PMID 39456468, 2024).
pancreatic cancer (5 papers, 2012 to 2025). "In a subsequent study we reported that expression of QSOX1 promotes pancreatic tumor cell growth and invasion." (PMID 23536962, 2013). "Based on our previous results showing that QSOX1 over-expression in pancreas tumor cells contributes to invasion, we hypothesized that the over-expression of QSOX1 in breast adenocarcinoma would elicit a similar phenotype." (PMID 23536962, 2013). "Hypoxia plays a critical role in pancreatic cancer progression by inducing HIF1 to activate numerous genes involved in invasion and metastasis, such as NF-κB, MMP-2, quiescin-sulfhydryl-oxidase-1 (QSOX1), CX3CR1, and lysyl-oxidase (LOX)." (PMID 30060755, 2018).
colorectal cancer (3 papers, 2021 to 2024). A primary or metastatic malignant neoplasm that affects the colon or rectum. "Decreased QSOX1 protein levels in exosomes from patients with colorectal cancer have been recently identified, which might serve as an indicator for malignant transformation in CRC." (PMID 34885085, 2021).
breast tumor (2 papers, 2013 to 2018). "We were able to confirm that expression of QSOX1 significantly correlates with ER+ breast tumor (P = 0.0013) cells as well as correlating with high Ki-67 expression (P = 0.0011), further supporting a role for QSOX1 in cellular proliferation." (PMID 23536962, 2013). "The expression of QSOX1 correlates with increasing tumor grade as well as poor overall survival in patients diagnosed with grade 2 (P = 0.04242) and grade 3 (P = 0.07095) breast tumors." (PMID 23536962, 2013). "Since knockdown of QSOX1 resulted in decreased breast tumor cell invasion, it was important to determine a mechanism for how QSOX1 might facilitate invasion." (PMID 23536962, 2013). "Suppression of QSOX1 protein slowed cell proliferation as well as dramatic inhibition of MCF7, BT474 and BT549 breast tumor cells from invading through MatrigelTM in a modified Boyden chamber assay." (PMID 23536962, 2013). "Additionally, over-expression of QSOX1 mRNA in the GOBO analysis and high levels of protein in IHC correlate with increasing tumor grade in our breast tumor TMA analyses." (PMID 23536962, 2013).
glioblastoma (2 papers, 2024). The most malignant astrocytic tumor (WHO grade IV). "In glioblastoma, QSOX1 recently was found to be involved in cell viability, cell motility, and tumor size using established GBM cell lines." (PMID 39518060, 2024). "Recent studies have shown QSOX1 to be upregulated in a number of cancers such as pancreatic, prostate, breast, esophageal, melanoma, lung, and glioblastoma (GBM)." (PMID 39518060, 2024).
neuroblastoma (2 papers, 2014 to 2018). Neuroblastoma (NB) is the most common solid, extracranial childhood tumor. "Moreover, a genome-wide targeting more than 200 genes has shown that QSOX1 (QSCN6) could inhibit autophagy in human neuroblastoma cells by negatively regulating PI3K activity." (PMID 24475161, 2014).
Obesity (2 papers, 2017 to 2022). Accumulation of substantial excess body fat. "Additionally, differential methylation at the CpG sites of TOMM20, PSMB1, and QSOX1 was associated with all-cause mortality, suggesting that obesity-related dysregulation may, in part, drive mortality differences." (PMID 35752704, 2022). "In a study that examined the association between obesity and DNA methylation in NHB and NHW women diagnosed with breast cancer, the authors detected interactions with ER status (PSMB1, QSOX1, and PHF1) and race (TOMM20) among the top 20 obesity-associated CpG cites." (PMID 35752704, 2022). "Additionally, genes FSTL3, QSOX1 and SERPINE2 could serve as novel obesity-related biomarkers, as they have been shown to be uniquely enriched in the placenta, and we detected them as down-regulated among the placentas from obese women." (PMID 28125591, 2017).
preeclampsia (2 papers, 2013 to 2021). Preeclampsia is a hypertensive disorder of pregnancy that is characterized by new-onset hypertension with proteinuria presenting after 20 weeks of gestation, and depending on mild or severe forms may initially present with severe headache, visual disturbances, and hyperreflexia. "Among these genes, LAMB2, PTK2, RAC1, QSOX1, FN1, and VCAM1 have known associations with the pathogenic mechanisms of preeclampsia." (PMID 35719905, 2021). "QSOX1 protein is found in circulating extracellular vesicles of both preeclampsia and healthy pregnant women." (PMID 35719905, 2021). "Other genes as SPAG4, HEXB, TPI1 and QSOX1 are basically unknown in preeclampsia (and even during normal pregnancy)." (PMID 24219996, 2013). "Hypoxia-induced upregulation of Quiescin Sulfhydryl oxidase 1 (QSOX1) and an elevation in intracellular H2O2 leads to increased apoptosis in the placentae of pregnancies complicated by preeclampsia." (PMID 35719905, 2021).
Sepsis (2 papers, 2020 to 2022). Sepsis is defined as life-threatening organ dysfunction caused by a dysregulated host response to infection. "Expression of HP, QSOX1 (HR = 1.129, p > 0.05), and PGLYRP1 (HR = 1.062, p > 0.05) did not have a statistically significant predictive effect on the survival of patients with sepsis." (PMID 35145983, 2022).
astrocytoma (1 paper, 2022). "Among these, Sulfhydryl oxidase 1 (Qsox1), involved in tumor cell invasion and subsequent metastasis was found downregulated in cluster 1 such as CD166, TIMP2 and AGT knew to be involved in astrocytoma (cluster 1)." (PMID 33402730, 2022).
blastoma (1 paper, 2021). A malignant neoplasm composed of undifferentiated cells. "The QSOX2 gene encodes quiescin sulfhydryl oxidase 2, a member of the sulfhydryl oxidase/quiescin-6 (Q6) family (QSOX1), which are involved in the sensitization of neuro-blastoma cells for IFN-gamma (IFNG)-induced cell death." (PMID 34205581, 2021).
brain tumor (1 paper, 2024). "To determine the role of QSOX1 in GBM cell invasiveness, we used our xenograft chick embryo brain tumor model for these experiments." (PMID 39518060, 2024). "Here, we investigated the potential role of the cellular enzyme QSOX1, which creates specific bonds within proteins, in GBM cell proliferation, migration in a dish, and invasion into brain tissue in our chick embryo brain tumor model system." (PMID 39518060, 2024).
colitis (1 paper, 2023). Inflammation of the colon. "Importantly, we show here that administration of QSOX1 inhibitory antibodies did not potentiate DSS‐induced colitis, demonstrating that QSOX1 activity in colon physiology, and probably the Golgi functions of QSOX1 in general, are protected from inhibition by systemic inhibitory antibody treatment." (PMID 36245281, 2023).